IL6 (interleukin 6)
Diseases named in the same sentence as IL6 in open-access papers (continued):
Sharing a sentence is not in itself a finding about the gene and the disease.
tumor (continued). "Inflammatory biomarkers (such as TNF-α, IL-1, IL-6, vascular endothelial growth factor, matrix metalloproteinases) may lead to metastases, tumor progression and inefficiency of adjuvant chemotherapy." (PMID 35955993, 2022). "In addition, increased levels of circulating fibrinogen can induce the synthesis of interleukin 6 (IL-6) and promote tumor progression." (PMID 35062908, 2022). "Except immunomodulation, the mechanism of tumor growth inhibition may be related to the regulation of apoptosis related proteins and IL-6/STAT3 pathway." (PMID 35577774, 2022). "Importantly, IL-6 expression was lower in V-125-treated tumors, suggesting that V-125 plays a role in modulating the tumor immune compartment." (PMID 34997154, 2022). "One hypothesis is that M2 macrophages can inhibit PGK1 phosphorylation by secreting IL-6 to disrupt the connection between macrophages and tumor cells." (PMID 35875135, 2022). "The secreted periostin, a multifunctional ECM protein, the active participation of CAFs in the metabolism of tumor cells and the mediated IL-6 could elucidate the malignant proliferation of CAFs." (PMID 36139552, 2022). "On one hand, this secretome could be deleterious, as IL-1β might increase vascular permeability, and IL-6 could inhibit dendritic cells (DCs), support tumor cell migration, and, just like IL-8, is able to promote tumor growth." (PMID 35563820, 2022). "High level of IL-6 secretion may facilitate tumor cell growth via suppressing apoptosis and promoting angiogenesis." (PMID 35924148, 2022). "Similarly, a reduction in tumor weight and serum inflammatory cytokine IL-6 levels were observed in 4T1 breast cancer cells that had been transplanted to Asc-supplemented GULO−/− mice." (PMID 36234722, 2022). "In addition, the increased protein concentration of IL-6 observed in tumour of LLC mice treated with doxorubicin chemotherapy is mitigated by 3-weeks of moderate exercise training on a treadmill (40–60 min at 60% of maximum speed, 5 days/week)." (PMID 35626116, 2022). "In addition, elevated LONP1 expression increases the level of ROS to promote the production of inflammatory cytokines, including TGF-β and IL-6, thus boosting the activation of M2 macrophages and establishing an immunosuppressive tumor microenvironment." (PMID 35180892, 2022). "Furthermore, IL-6 induces pre-cancerous progenitor cell proliferation and transformation into tumor initiating cells." (PMID 36276076, 2022). "Furthermore, combining anti-VEGF blockade with inhibition of IL-6 plus chemotherapeutic agent doxorubicin in obese mice delayed tumor progression similar to lean mice on VEGF blockade and doxorubicin." (PMID 35186923, 2022). "and others, IL-6 can further increase naïve and central memory T cell trafficking to the tumor." (PMID 36532027, 2022). "A positively corelated expression pattern of IL-6 and Glut5 was found in all the three tumor types." (PMID 35813468, 2022). "The antitumorigenic immune components of tumor microenvironment are natural killer (NK) cells, dendritic cells (DC), cytotoxic T lymphocytes (CTLs), and M1 tumor-associated macrophages (M1 TAMS) secreting mainly proinflammatory cytokines like IL-1β, IL-1α, IL-6, IFNγ, TNFα etc.." (PMID 36496977, 2022). "Nevertheless, there is mixed evidence that regular exercise reduces these inflammatory mediators in the tumour microenvironment – in fact some studies show that IL-6 may be increased by exercise, and this corresponds to enhanced anti-tumour responses." (PMID 35359426, 2022). "Research from our group demonstrated that voluntary wheel running led to mobilization and redistribution of epinephrine‐sensitive natural killer (NK) cells to the tumors, partly by an interleukin (IL)‐6‐dependent mechanism leading to a suppression of tumor growth in mice." (PMID 36199257, 2022). "Recently, IL6 blockade was shown to exert anti-tumor effects in tumor bearing mice." (PMID 35449550, 2022).
tumor (continued). "Furthermore, proinflammatory cytokines, such as TNF-α, IL-6, and IL-1β, secreted by activated cells are known to be involved in the destruction of pathogens and tumor cells." (PMID 36422317, 2022). "However, monocytes in the TME are influenced by tumor-derived cytokines (i.e., M-CSF, IL-10, IL-6, and TGF-β) and differentiate into tumor-promoting M2-type macrophages (i.e., tumor-associated macrophages, TAMs; Quail and Joyce, 2013)." (PMID 36408222, 2022). "In addition, it seems that IL-6 strengthens angiogenesis by stimulating the expression of vascular endothelial growth factor receptor 2 (VEGFR2) on the surface of tumor cells." (PMID 35410210, 2022). "However, the combination of NVP-BEZ235 and anti-IL-6 Ab significantly suppressed tumour progression." (PMID 35165269, 2022). "Therefore, the authors determined the content of CASP3, TNFα, and IL6 inflammatory factors in the serum of the xenograft tumor model." (PMID 35815259, 2022). "Moreover, our experiments revealed that PC3RR cells secrete factors, such as IL-6, capable of stimulating the bone erosion that creates the physical space in which tumour cells can grow and reach a critical mass." (PMID 36428597, 2022). "During the process of tumor cell death, inflammation could be induced and related inflammatory cytokines such as TNF-α, IL-1β, and IL-6 further cause immune cell infiltration, which further results in the elimination of dead cells." (PMID 35402247, 2022). "Furthermore, TGF-β enhances the epithelial-to-mesenchymal transition (EMT), synergistically triggering tumor metastasis with IL-6 via the overactivation of JAK/STAT signaling pathways." (PMID 36613591, 2022). "IL-6 may also play a role in a variety of features of tumor behavior, including apoptosis, proliferation, migration, and invasion, as well as angiogenesis and metastasis." (PMID 35204188, 2022). "Herein, it may be effective for decreasing tumor chemotherapy resistance via targeting TAMs and related IL-6/STAT3 signaling pathways." (PMID 35193986, 2022). "MIF promotes the secretion of the inflammatory factor IL-6 in the hypoxic tumour microenvironment." (PMID 36042480, 2022). "In comparison with the control group, the observation group exhibited a lowered ADPN level (p<0.05), notably raised levels of plasma D-D, inflammatory factors hs-CRP and interleukin-6 (IL-6) and serum tumour markers CA125 and HE4 and an evidently increased ROMA (p<0.05)." (PMID 35431651, 2022). "Furthermore, the expression of both IL-1β and IL-6, which have the ability to enhance the immune response against tumours by activating CD8+ T cells was also markedly increased." (PMID 35057796, 2022). "In addition to sustaining tumor cells growth and assisting their metastatic ability, IL-6 was also reported to reduce cisplatin-triggered apoptosis in breast cancer cells via the STAT3 pathway." (PMID 36324128, 2022). "As CAR-T cells expand when interacting with the target tumor cells, massive cytokines including interleukin-6 (IL-6), interferon-γ (IFN-γ), monocyte chemoattractant protein 1 (MCP-1), and granulocyte-macrophage colony-stimulating factor (GM-CSF) were released by CAR-T cells and other immune cells." (PMID 36105799, 2022). "The IL-6 released to the tumor microenvironment activated IL-6/JAK/STAT3/PD-L1 in neutrophils." (PMID 36612180, 2022). "IL6 promotes tumor cell proliferation, survival, and metastasis through activation of Stat3." (PMID 35200587, 2022). "IL-6 clearly acts as a tumour promotion and progression factor." (PMID 35818030, 2022). "In addition, STAT3 activation by IL-6 and IL-8 produced by tumor cells has been reported to decrease levels of NKG2D and NKp30 on NK cells." (PMID 35865518, 2022). "High-serum IL-6 is associated with worse prognosis in non-small cell LC (NSCLC) patients, as increased IL-6 has been correlated with a lower 24-month survival rate and more advanced tumor staging." (PMID 35892857, 2022).
tumor (continued). "An increasing amount of evidence suggests that many proangiogenic factors which come from tumour cells, such as S1P, IL-6 and VEGFA, could induce the activation of STAT3 and stimulate the ECs of neighbouring blood vessels." (PMID 36068200, 2022). "Notably, endothelial cell activation requires the elevated expression of Snail1, which can strengthen CAF activation in a paracrine manner promoting immune infiltration in TME by secreting IL-6 in tumor development." (PMID 35479936, 2022). "Furthermore, emerging data suggest that GBM tumor cell-induced IL-6 displays a pro-tumorigenic role, and correlates with poor prognosis and GAM infiltration in GBM." (PMID 35572545, 2022). "Thus, our findings document that the interactive dialogue between TNBC cells and TAMs promotes sustained activation of HLF in tumor cells through the IL-6-TGF-β1 axis." (PMID 34991659, 2022). "In addition, Oncostatin M (member of the IL-6) contributes to tumour invasion as reported in human breast cancer (involved in vascular endothelial growth factor F (VEGF) induction) and mouse lung cancer (by accumulation of M2 macrophages)." (PMID 35406451, 2022). "Besides, RuPOP@CM can enhance the activity of cellular immune response and promote the production of inflammatory cytokines including TNF-α, IL-12 and IL-6, which is of great significance in treatment of tumor." (PMID 36064356, 2022). "Macrophages may internalize and secrete TNF- α, NO, IFN-γ, IL-2, IL-6, IL-8, IL-12 and IL-18, so as to play an anti-inflammatory and even anti-tumor role." (PMID 35299759, 2022). "Specifically, exercise can mobilize cytotoxic natural killer cells into circulating blood and can redistribute these cells to tumor cells with assistance from exercise-induced increases in circulating norepinephrine and IL-6; this process appears to require endurance exercise at high intensity." (PMID 36261844, 2022). "Moreover, the dysfunction of DC also attenuates CD4+ T-cell-mediated antitumor immunity responses, and inhibition of IL-6 reduces tumor growth by restoring T-cell activity in tumor-bearing mice." (PMID 36405719, 2022). "Higher IL-6 levels during treatment may be indicative of high tumor cell proliferation and enhanced angiogenesis, and immunotherapy will be less effective in eliminating this state." (PMID 36091125, 2022). "IL-6 is reported to play both promoting and suppressing roles in tumor immunity." (PMID 35205631, 2022). "Other studies showed that ZEB1 could promote tumor development via recruiting IL6 and IL8 in the tumor microenvironment." (PMID 35342335, 2022). "Inhibition of the IL‐6/JAK/STAT3 pathway suppressed tumor growth in the N‐inv model and could represent a candidate target for the treatment of PDAC." (PMID 35578571, 2022). "TAMs themselves secrete IL-6, IL-8, and IL-10 that promote tumor growth." (PMID 35892729, 2022). "Interleukin (IL)-6 and other proinflammatory cytokines, including tumor necrosis factor, are released by inflammatory cells in the tumor microenvironment in response to tissue necrosis and the presence of tumor cells." (PMID 36096761, 2022). "Therefore, IL-6 can contribute to the formation of the tumor immunosuppressive microenvironment by regulating various types of immune cells, such as T cells and MDSCs." (PMID 36422541, 2022). "Evidence has demonstrated a positive loop between astrocytes and microglia at the tumor site: the microglial cells release IL-6 that activates the peri-tumoral reactive astrocytes to secrete Monocyte Chemotactic Protein-3 (MCP-3) via JAK-STAT proteins, which further attracts more microglial cells." (PMID 35205842, 2022). "In sum, these studies suggest that TAM-associated tumor cell proliferation occurs in an IL-6 or IL-10/STAT3 signal cascade dependent manner and targeting proteins in the IL-6 or IL-10/STAT3 signaling pathway to attenuate tumor cell proliferation is promising in anti-tumor therapies." (PMID 35327584, 2022).
tumor (continued). "Interestingly, in the tumor microenvironment surrounding tumor cells, IL-6 is also produced by other kinds of cells, such as tumor-infiltrating immune cells and stromal cells, resulting in the hyperactivation of STAT3 signaling." (PMID 35956786, 2022). "Notably, adding a neutralizing antibody against IL6 to the coculture system of circCUL2-transduced NFs and tumor cells inhibited cancer cell metastasis." (PMID 35189958, 2022). "Moreover, studies have shown that USP24 promoted cancer malignant progression by stabilizing p300 and β-TrCP-induced IL-6 in the tumor microenvironment." (PMID 35223996, 2022). "One early activated URM is RAF1, a known oncogene but which is also capable of tumor suppressant activity related to decreased IL-6 and JAK/STAT3 signaling activity, and simultaneous IL-6 and STAT3 activation has been shown to promote tumor formation in gastrointestinal tissues." (PMID 34983392, 2022). "IL-6 plays a central role in aggressive tumor growth and treatment resistance." (PMID 35992826, 2022). "IL-6 was highly expressed in the tumor microenvironment; it could enhance the secretion of IL-1β and IL-18 and trigger the inflammatory storm in vivo." (PMID 35464414, 2022). "Furthermore, they assist tumor initiation and the mutagenic microenvironment by releasing circulating pro-inflammatory cytokines (IL6, TNF-α, and IFN-γ), growth factors (VEGF and EGF), ROS, and proteases." (PMID 35707536, 2022). "Moreover, patients with the IL6-rs2069837-AA genotype had higher tumor response (67% AA vs. 52% any G, p = 0.026) only in the validation cohort." (PMID 36432658, 2022). "Among them, the IL-6 promoter methylation value of HBV-related HCC patients with a tumor size >3 cm was sharply higher than that of patients with <3 cm Multivariate logistic regression analysis showed that hypomethylation of the IL-6 promoter is an independent risk factor of HCC." (PMID 35359408, 2022). "The current evidence suggests that PD-1/PD-L1 inhibition may regulate the IL-6/IL-17-neutrophil axis, resulting in abnormal inflammation, tumor immune escape, and accelerated tumor growth." (PMID 35681453, 2022). "Elevated serum levels of IL-6 indicate a poorer prognosis for tumor patients." (PMID 35965509, 2022). "Moreover, the availability of IL-6 is thought to act as a stimulus for immune effector cell infiltration to tumours in response to regular exercise." (PMID 35359426, 2022). "Furthermore, reduced FTO in combination with m6A modification of APOE can modulate the IL-6/JAK2/STAT3 signaling pathway to promote tumor glycolysis, thereby aggravating the progression of PTC." (PMID 36506554, 2022). "In order to test whether this photodynamic chemotherapy could mediate the immune response in tumor site, we measured the mRNA expression level of Il-2, Il-6, Il-10, Tnf-α, Tgf-β and Inf-γ in tumor issues." (PMID 35999549, 2022). "Moreover, the conversion of non-stem cancer cells to CSCs, such as in the case of trastuzumab resistance resulting in CSC proliferation, occurs predominantly as a result of IL-6 release by CSCs in the tumor microenvironment." (PMID 35409206, 2022). "At the tumor site, BMDSCs also have the capacity to differentiate into angiogenesis-promoting endothelial cells, or TAFs as a source of extracellular protease expression, TGF-β, VEGF, CXCL-12, -14, -16, CCL2-5, IL-4 or IL-6, the collective interplay of which contributes to tumor progression." (PMID 34918208, 2022). "Tumor-associated macrophages (TAM), myeloid-derived stem cells (MDSC), and lymphocytes Th1/Tc infiltrating the TME influence the epithelial cells undergoing TME through the secretion of IL-1β, IL6, IL8, IL10, IL17, TGF-β, or TNFα." (PMID 35884974, 2022). "The authors could observe activation in a subset of fibroblasts, and found evidence for interleukin 6 (IL6)-mediated signalling between tumour cells and stroma, contributing to their survival and growth." (PMID 35328567, 2022).
tumor (continued). "Similarly, IL-6 produced by CAFs was evidenced to endow tumor-initiating characteristics to HCC cells by the enrichment of STAT3/Notch signaling." (PMID 36293184, 2022). "Although IL6 signaling in tumor microenvironment might be considered as a bad player that promotes tumor progression, recent research shows that IL6 signaling mobilize T cell immune response to control tumor progression." (PMID 36326318, 2022). "Our result here demonstrated that neoantigen vaccination could downregulate the expression of tumor-promoting cytokines such as IL-6 to help achieve better clinical response." (PMID 36248865, 2022). "Peri-tumor fibroblasts also produced more IL-6, which induce HCC stemness via IL-6-STAT3-pathway." (PMID 35971182, 2022). "When IL-6 signaling inhibited, the effects of S. mutans on tumor aggressiveness were attenuated." (PMID 36186905, 2022). "Such systematic abnormalities were ascribed to an overproduction of interleukin 6 (IL-6), which could disappear after the removal of the tumor." (PMID 36438949, 2022). "Hallmark pathways involved in immune response were also very highly enriched in tumor epithelium compared with normal, including interferon-α and interferon-γ response, interleukin-6 (IL-6)/Janus kinase (JAK)/signal transducer and activator of transcription 3 (STAT3) signaling, and NF-κB signaling." (PMID 35394843, 2022). "Some crucial cytokines, including G-CSF, IL-1β, VEGF, and IL-6 from tumor cells, could potentially increase the number of neutrophils in peripheral blood and tumor tissue." (PMID 36556130, 2022). "Studies have shown that dysregulated IL-6 or JAK2 can reprogram the STAT3 pathway in metastatic tumor cells, induce recruitment of myeloid-derived suppressor cells (MDSCs) and polarized macrophages, and repress the infiltration of CD8+ T cells to evade host immunity in NSCLC." (PMID 36559280, 2022). "Indeed, our results show that STAT3 activation mediated by elevated IL-6 plasma concentration and oxidative damage in skeletal muscle plays a key role in tumor-induced muscle atrophy." (PMID 35847939, 2022). "Moreover, resistance to VEGFR TKI treatment can lead to cellular changes resembling senescence-associated secretory phenotypes (SASPs), promoting recurrence of tumor growth and cancer progression regulated by mTOR signaling and IL6." (PMID 36138026, 2022). "Diacerin treatment reduces protein expression of IL-6Rα, pSTAT3, pMAPK, pAKT in TNBC tumor sections indicating diacerin could inhibit multiple IL-6-regulated oncogenic pathways." (PMID 35371975, 2022). "Notably, much smaller tumor volumes, lower serum IL-6 levels comparable to those of healthy mice, and larger calf circumference were detected in MBT-2/CSi-Hotair-bearing mice than in MBT-2/CSi-GFP-bearing mice." (PMID 36471329, 2022). "Although TAMs can also be broadly divided into M1 and M2 phenotypes, it is believed that most resident TAMs exhibit a M2-like phenotype induced by chemokines, tumor-derived cytokines, and proteases, such as IL-4, IL-6, IL-10, TGF-β1, and polyethylene glycol (PEG)." (PMID 35625939, 2022). "Here, IL-6, promoted by the tumour microenvironment, may interact in concert with G-CSF to drive neutrophil protumour activity and also production of CXCL13." (PMID 35226704, 2022). "Indeed, blocking β-adrenergic pathways or IL-6 function in tumour-bearing mice dampened the aerobic exercise-dependent suppression of tumour growth." (PMID 36291823, 2022). "TAMs induce EMT in tumor cells by secreting a host of cytokines and growth factors, such as transforming growth factor-beta (TGF-β), tumor necrosis factor-α (TNF-α), interleukin-6 (IL-6), and interleukin-8 (IL-8), thereby promoting tumor invasion and metastasis." (PMID 35965509, 2022). "Moreover, IL‐6, a multipotent immunosuppressor that is expressed in DCs, facilitates immune evasion of tumor cells in the CRC TME via complex signaling pathways." (PMID 35791509, 2022).